IL6 (interleukin 6)
Diseases named in the same sentence as IL6 in open-access papers (continued):
Sharing a sentence is not in itself a finding about the gene and the disease.
Sepsis (continued). "We first evaluated the serum levels of lactate, LDH, the inflammatory cytokine IL6, and the EC activation‐related molecules soluble E‐selectin (sE‐selectin), sICAM1, and sVCAM1, as well as their correlations in patients with sepsis." (PMID 39822760, 2025). "Our results showed that the expression of IL-10 on day +7 (P = 0.005), TNF-α and IL-6 on day +14 (P = 0.041 and P =0.010), and IL-6 on day +28 (P = 0.010) were higher in patients with sepsis than the control group." (PMID 40718494, 2025). "Interleukin-6 has been reported to be positively correlated with EG biomarkers in people with sepsis and trauma and was a significant predictor of HA concentration in the previously referenced series of 8 dogs with septic peritonitis." (PMID 40512747, 2025). "Interleukins are produced by many WBCs and are involved in the differentiation and activation of other immune cells, with IL-1β, IL-6, and IL-10 being the most studied in the context of sepsis." (PMID 39968295, 2025). "IL-6, a pro-inflammatory cytokine, is a key regulator of immune responses in sepsis and contributes to renal damage." (PMID 41281283, 2025). "Overall, while UC IL-6 demonstrates significant potential as an early biomarker for neonatal sepsis, the heterogeneity of reported cut-off values underscores the need for further large-scale, standardized studies to establish clinically reliable thresholds." (PMID 41302151, 2025). "In the context of sepsis, activation of these TLRs triggers the synthesis and release of various cytokines from immune cells, including TNFα, IL-6, and IL-12, driving the excessive inflammatory response." (PMID 39968295, 2025). "In humans, IL-4 and IL-10 levels rise during the recovery phase of SIRS and sepsis, although they typically remain lower than pro-inflammatory cytokines such as IL-6 and TNF-α." (PMID 40584120, 2025). "The findings revealed that the combination of S100A9 with APACHE II and IL-6 significantly enhanced the ability to predict sepsis-related mortality." (PMID 40478888, 2025). "This prospective observational study demonstrated that PCT is a significantly more reliable and earlier indicator of postoperative sepsis than CRP or IL-6 in patients undergoing lung decortication." (PMID 41281040, 2025). "MCP-1, IL-6, and IL-10 levels are significantly elevated at d0 in both sepsis groups compared to healthy controls (p < 0.05)." (PMID 40510342, 2025). "IL-6 is a key inflammatory marker that plays a significant role in diagnosing and progressing sepsis by interacting with various cytokines." (PMID 40635709, 2025). "In this study, hepatocyte-specific HNF4α knockout mice displayed reduced expression and activity of PPARα, diminished IL6-induced acute phase response, and increased mortality from sepsis." (PMID 40061452, 2025). "Another crucial immunological target in sepsis is the pleiotropic cytokine interleukin-6 (IL-6), which plays a central role in organ dysfunction and sepsis-related mortality." (PMID 41268545, 2025). "When sepsis occurs, the inflammatory factors IL-6 and TNF-α released at the early stage in the body can bind with STAT3, activate it, and enhance IL-6 and TNF-α transcription in the nucleus." (PMID 40338919, 2025). "IL-6 is a pro-inflammatory cytokine that serves as a rapid indicator of inflammation and assists in diagnosing infection during sepsis." (PMID 41517447, 2025). "For example, in a prospective cohort of ICU patients with SIRS or sepsis, plasma IL-6 levels on day 3 were strongly predictive of ICU mortality, with concentrations >124.14 pg/mL associated with a six-fold increase in the risk of death." (PMID 41300951, 2025). "Among these cytokines, interleukin-6 (IL-6) holds particular significance in the pathogenesis of sepsis, notably serving as an early indicator of inflammation." (PMID 39930418, 2025). "For instance, in a mouse model of cardiac dysfunction induced by sepsis, pre-treatment with losartan reversed the increase in IL-1β, IL-6, TNF-α, and MCP-1." (PMID 40647187, 2025).
Sepsis (continued). "Given the dynamic nature of GC and cytokine production in sepsis, timely measurement of GCs and IL-6 is crucial." (PMID 40048257, 2025). "Based on these results, we cannot conclude that IL-6 levels within the first 96 h after admission have significant prognostic value for predicting mortality in sepsis patients using logistic regression." (PMID 40149943, 2025). "Sepsis is defined by the impairment of the immune system, which is closely linked to an overabundance of proinflammatory cytokines like TNF-α, IL-1β, and IL-6." (PMID 40144662, 2025). "Interleukin-6 (IL-6) is a central mediator of systemic inflammation and is markedly elevated in critical illnesses, including sepsis, acute respiratory distress syndrome, and hyperinflammatory syndromes." (PMID 41155261, 2025). "In conclusion, this study presented a logistic regression-based model combining RDW, APACHE II, and additional biomarkers (PCT, IL-6, CRP, and cystatin C) to predict AKI risk in children with sepsis." (PMID 41281283, 2025). "Lastly, relying on a single biomarker like IL-6 to predict mortality in a complex syndrome like sepsis has inherent limitations." (PMID 40149943, 2025). "Among these physiological effects affectedby IL-6, sepsis is adysregulated systemic immune response to infection." (PMID 39907592, 2025). "Elevated IL-6 has also been reported in a recent publication in dogs with organ dysfunction secondary to sepsis and evidence of EG degradation." (PMID 40512747, 2025). "Overall, the results showed that IL-6 is a more reliable indicator of newborn sepsis, showing improved performance and sensitivity in both EOS and culture-negative cases." (PMID 40242671, 2025). "Interleukin-6 mediated sepsis-induced muscle atrophy through the gp130/JAK2/STAT3 pathway in a mouse model of sepsis, indicating the possibility of ICU-acquired weakness." (PMID 40708825, 2025). "Studies were included if they assessed the independent prognostic value of IL-6 in adult sepsis patients, used well-defined sepsis criteria, and reported at least one IL-6 measurement." (PMID 40149943, 2025). "The overwhelming production of proinflammatory cytokines, such as interleukin (IL)-1β, IL-6, tumor necrosis factor (TNF)-α, as well as reactive oxygen species (ROS) is a hallmark of sepsis and sepsis-associated AKI." (PMID 40656894, 2025). "In pediatric sepsis, IL-6 plays a dual role as both an inflammatory mediator and a biomarker of severity." (PMID 41300951, 2025). "Collectively, our data highlight the potential utility of IL-6 in conjunction with an elevated granulocyte-to-lymphocyte ratio as promising early indicators of concomitant liver stress in sepsis." (PMID 40178612, 2025). "Elevated IL-6 has also been associated with organ-specific dysfunctions such as acute kidney injury (AKI), acute respiratory distress syndrome (ARDS), and sepsis-associated myocardial depression." (PMID 41300951, 2025). "The data were presented using hierarchical clustering to better observe the behavior of IL-6, lung injury, and kidney injury during the sepsis process and better understand their changes." (PMID 39955435, 2025). "The combined use of admission-day biomarkers reflecting inflammation (IL-6), coagulation (PT-INR), and immunometabolism (HDL) provides a powerful and synergistic tool for early risk stratification in severe sepsis." (PMID 40959673, 2025). "Inflammatory mediators that are commonly elevated during the acute phase of sepsis include interleukins (IL)-1β, IL-6, IL-8, CC motif chemokine ligand 2 (CCL2) and tumour necrosis factor (TNF)-α." (PMID 41124072, 2025). "Serum IL-6 levels increased significantly at 2nd hour compared to hour 0 following sepsis induction; IL-6 levels peaked at 4th hour and were higher at 6th hour compared to 2nd hour but lower than at 4th hour." (PMID 39955435, 2025).
Sepsis (continued). "Tα1 inhibits the expressions of TNF-α and IL-6 in sepsis rats and weakens the activity of the Notch signaling pathway, thereby preventing the progression of inflammation and alleviating sepsis-induced lung injury." (PMID 40599771, 2025). "Cytokines play a pivotal role in host defense during sepsis, with key mediators such as tumor necrosis factor-α (TNF-α), interleukin (IL)-1, IL-6, and IL-10 implicated in its pathophysiology." (PMID 40944015, 2025). "It is of relevance to the effective management of sepsis that the NTCI peptide suppressed the mediators of inflammation in the blood (IL-6, IL-10, TNFα, Interferon γ, and MCP1)." (PMID 41229427, 2025). "In sepsis and other hyperinflammatory states, IL-6 surges are extreme, leading to marked fibrinogen overproduction alongside albumin suppression, creating a hypercoagulable yet hypoalbuminemic state." (PMID 41157266, 2025). "In contrast, IL-6 levels are significantly elevated and function as a biomarker of outcomes in patients with sepsis (Merz & Thurmond, 2020; Shamim, Hawley & Camera, 2018)." (PMID 40708825, 2025). "In these patients, CRP and IL-6 were found to increase due to sepsis, and its effect on prognosis was emphasized." (PMID 40005437, 2025). "Despite these limitations, our findings provide valuable insights into IL-6 levels in patients with sepsis." (PMID 39800741, 2025). "Elevated IL-6 levels indicate an acute inflammatory response, commonly seen in sepsis, which can contribute to neuronal injury and dysfunction, potentially leading to SAE." (PMID 40635709, 2025). "IL-6 contributes to the dysregulated immune response in sepsis, which can lead to systemic inflammation and organ failure." (PMID 40497942, 2025). "During the initial phase of SAP or sepsis, a massive release of pro‐inflammatory cytokines (e.g., IL‐6, TNF‐α) establishes a critical immunoregulatory imbalance." (PMID 40464424, 2025). "Recently, different types of biomarkers, such as tumor necrosis factor-α, IL-6, cluster of differentiation 64, and miRNAs, have shown clinical application in patients with sepsis." (PMID 40478618, 2025). "Previous studies have reported the values of IL-6 and IL-8 in the early diagnosis of sepsis in children and newborns." (PMID 39886481, 2025). "Our research revealed that Il6 was among the main genes that were upregulated in the sepsis group, consistent with its established function as a significant player in the acute phase response." (PMID 40792069, 2025). "Nowadays, Interleukin (IL)-6 is widely regarding as the center of CS and another biomarker for sepsis." (PMID 39891057, 2025). "In the early stage of LPS-induced sepsis, IL-6 supplementation promotes the expression and nuclear translocation of nuclear factor E2-related factor 2 (Nrf2), thereby maintaining the redox homeostasis of myocardial cells." (PMID 40520010, 2025). "The aim of this study is to investigate the utility of IL-6 as a biomarker for differentiating between sepsis and NEC, and between medical and surgical NEC cases, in a large cohort of infants with suspected LOS." (PMID 39958363, 2025). "In some infants, such as subjects 4 and 8, elevated levels of inflammatory markers (CRP and IL-6) and sepsis coincided with increased circulating CD34+ cell counts." (PMID 41147034, 2025). "IL-6, as a central cytokine in the early inflammatory response of sepsis, exerts its effects through the JAK/STAT3 signaling pathway." (PMID 40297590, 2025). "In response to sepsis, plasma IL-6 increased significantly in both temperature groups and were significantly higher (p = 0.04) in the 30°C group (3.8 ± 3.3 x103 pg/mL) compared to the 22°C group (1.9 ± 1.3 x103 pg/mL)." (PMID 40445962, 2025). "The serum Interleukin 6 (IL-6) level was significant higher in elderly sepsis patients (128 versus 43.8pg/ml, P=0.043)." (PMID 40933998, 2025).
Sepsis (continued). "The indication for the use of CytoSorb was sepsis in 11 patients and hemophagocytic syndrome in one patient; in these patients, the baseline IL-6 level was >500 ng/L." (PMID 41140657, 2025). "During sepsis, LPS stimulation elevates the expression and release of proinflammatory cytokines, including IL-6 and TNF-α." (PMID 41256846, 2025). "IL-27, a member of the IL-6/IL-12 family, plays a complex role in abnormal immune inflammation that occurs during sepsis." (PMID 40046257, 2025). "Secretion of inflammatory cytokines like interleukin (IL)-6 during sepsis leads to the production of acute-phase proteins such as C-reactive proteins, which in turn results in inhibition of the protein C pathway, and thus increases coagulation activity." (PMID 40845038, 2025). "In the present study, we have shown that IL-6 is an independent inflammatory marker because we evaluated DKA patients excluding sepsis and infection." (PMID 40005437, 2025). "In patients with sepsis, CECs are expanded in the peripheral blood, and their frequencies are positively correlated with high levels of interleukin (IL)‐6 and interferon (IFN)‐γ." (PMID 41381803, 2025). "Both immunoparalysis, indicated by reduced ex vivo cytokine production, and hyper-inflammation, characterized by elevated levels of IL-6, IL-8 and TNFR1, are associated with worse outcomes in sepsis." (PMID 40433392, 2025). "During sepsis, massive pro-inflammatory mediators (IL-6, TNF-α, etc.)drive hepatic acute phase response, leading to dramatic elevation of SF." (PMID 41323136, 2025). "This study evaluates the IL-6/PCT ratio as a biomarker to distinguish CRS from sepsis in patients with haematological malignancies receiving CAR-T therapy." (PMID 41347097, 2025). "Examining the relationship between serum levels in IL-6, lung injury, and kidney injury was crucial in predicting the timing of treatment application in sepsis patients." (PMID 39955435, 2025). "For example, in a mouse sepsis model, sEVs have been shown to contain pro-inflammatory cytokines such as Interleukin (IL)-1β, IL-2, IL-6, and TNF-α at early stages, followed by IL-12, IL-15, IL-17, and IFN-γ at late stages." (PMID 41010852, 2025). "A large-scale trial enrolling sepsis patients across diverse geographical regions of India is needed to confirm the prognostic accuracy of the IL-6, PT-INR, and HDL biomarker panel and to establish the generalizability of the proposed risk prediction model." (PMID 40959673, 2025). "When we performed immunomodulation assays through qPCR, we found that the infected mice treated with fermented milk (D1(7d)) exhibited a reduced IL-6 and IFN-γ expression, which is associated with the process of sepsis and mortality in these animals." (PMID 41156807, 2025). "Several pro-inflammatory cytokines, such as MCP-1 and IL-6, were significantly elevated in both sepsis groups compared to healthy controls." (PMID 40510342, 2025). "For instance, sepsis-induced IL-6 has been shown to promote the expansion of MDSCs, a heterogeneous population of immature myeloid cells that suppress T cell function and promote tumor growth." (PMID 40563999, 2025). "The inflammatory environment in septic patients is highly complex, involving a combination of pro-inflammatory cytokines associated with the systemic inflammatory response characteristic of sepsis (e.g., IL-1β, IL-6, TNF-α, and interferon-γ)." (PMID 40950553, 2025). "While IL-6 is recognized as a prognostic marker in sepsis broadly, several features make it particularly relevant to melioidosis pathophysiology." (PMID 41439926, 2025). "During sepsis, hepatocytes respond to the stimulation of the cytokines in the serum such as IL-6, IL-1β, producing a significant amount of APP to combat bacteria and regulate the immune response." (PMID 40061452, 2025).
Sepsis (continued). "IL-6 levels were significantly elevated in the sepsis group and all TCZ-treated groups compared to the healthy group, with a lower increase in the TCZ1 group than in the sepsis and other TCZ treatment groups." (PMID 39955435, 2025). "IL-6 determined from umbilical cord blood or neonates’ serum at 0–12 h of life, while biologically plausible as a sepsis marker as reported in several studies, showed limited sensitivity (22–44%), despite high specificity (93–100%)." (PMID 40506913, 2025). "In the sepsis group, there was a notable increase in the expression of Cxcl10, Il6, and Stat1, which aligns with the findings from the RNA-seq data." (PMID 40792069, 2025). "Compared to C-reactive protein (CRP) and procalcitonin (PCT), IL-6 performs better for early sepsis diagnosis." (PMID 39857702, 2025). "Various other biomarkers, including CD64, presepsin, interleukin-6, and adrenomedullin have been evaluated and reported to provide valuable information for identifying sepsis and predicting clinical outcomes." (PMID 41225969, 2025). "In sepsis-associated AHI, mononuclear or macrophage-derived IL-6 and IL-1 are over-released, leading to liver microcirculation failure, mitochondrial dysfunction, and hepatocyte injury." (PMID 40046257, 2025). "The peripheral blood inflammatory markers in patients with sepsis are the primary outcome measures of this study, including IL-6, TNF-α, and CRP." (PMID 41195185, 2025). "It has been shown previously that interleukin-6 (IL-6) can predict sepsis, and its non-invasive determination can be performed quickly, leading to the diagnosis and appropriate treatment for each case." (PMID 40242671, 2025). "reveals IL-6 exerts cardioprotective effects against oxidative stress during early LPS-induced sepsis." (PMID 41256846, 2025). "The results demonstrated that IL-6, PCT, CRP, IL-8, and NEU% exhibited robust diagnostic value in the diagnosis, differential diagnosis, and prognosis of sepsis." (PMID 40264754, 2025). "Hamed and colleagues, for example, investigated the usefulness of PTX3 in septic patients and found that it was as useful as IL-6 in diagnosing sepsis and septic shock in the first week of intensive care therapy." (PMID 40426899, 2025). "LPS-induced sepsis model was established in rats to assess the changes in interleukin-6 (IL-6) over a 24-h sepsis period and its correlation with lung and kidney injury." (PMID 39955435, 2025). "In the previous studies, IL-6 and its receptors were considered as the key nodes in immunotherapies of sepsis." (PMID 39891057, 2025). "Second, IL-6 has demonstrated prognostic value across multiple sepsis contexts, including community-acquired pneumonia, Gram-negative bacteremia, and polymicrobial sepsis." (PMID 41439926, 2025). "In bacterial infections, particularly sepsis, IL-38 reduces the release of pro-inflammatory cytokines (IL-6, TNF-α, IL-17) and promotes regulatory T cell responses, thereby mitigating tissue injury and improving survival in experimental models." (PMID 41300951, 2025). "In this scenario, proinflammatory cytokines, such as TNF-α, IL-1β, and IL-6, have been confirmed to act in the acute phase of sepsis, mediating the systemic response and progression to multiorgan dysfunction." (PMID 41268545, 2025). "HMGB1 is thought to act as a late mediator because the kinetics of its release is delayed compared with most other cytokines such as IL-6 in sepsis." (PMID 39849347, 2025). "Vitamins A and VD deficiencies were associated with lower serum levels in geriatric sepsis patients and were inversely correlated with PCT and IL-6." (PMID 41311806, 2025). "Systemic inflammation was assessed by measuring TNF-α, IL-1β, IL-6, and MCP-1, which are hallmark inflammatory mediators of sepsis." (PMID 40185975, 2025). "IL-6 is a highly sensitive biomarker for systemic inflammation, particularly in sepsis and ARDS, often rising before clinical deterioration." (PMID 40310334, 2025).